KRTAP9-6 (keratin associated protein 9-6)
Description:
In the hair cortex, hair keratin intermediate filaments are embedded in an interfilamentous matrix, consisting of hair keratin-associated proteins (KRTAP), which are essential for the formation of a rigid and resistant hair shaft through their extensive disulfide bond cross-linking with abundant cysteine residues of hair keratins. The matrix proteins include the high-sulfur and high-glycine-tyrosine keratins (By similarity).
Synonyms: KAP9.6; KRTAP9.6; KRTAP9L2
Tractability: No criterion of Open Targets' tractability assessment is met for any kind of drug.
Gene: Protein-coding gene on chromosome 17 (41,265,378 to 41,265,860, forward strand). Ensembl gene ENSG00000212659.
Pathways (Reactome):
Developmental Biology: Keratinization
Gene Ontology:
Cellular component: cytosol; keratin filament
Genetic constraint (gnomAD): Loss-of-function variants: 5 observed, 7.28 expected, observed/expected ratio (o/e) 0.69, 90% interval 0.36 to 1.43. That is too few expected variants to judge how well the gene tolerates losing a copy. Missense variants: 68 observed, 97.56 expected, observed/expected ratio (o/e) 0.7, 90% interval 0.57 to 0.85. Synonymous variants: 31 observed, 31.35 expected, observed/expected ratio (o/e) 0.99, 90% interval 0.74 to 1.34.
Homologues: Paralogues in human: KRTAP9-2 (92% identical), KRTAP9-9 (89% identical), KRTAP9-7 (87% identical), KRTAP9-3 (83% identical), KRTAP9-4 (82% identical), KRTAP9-8 (80% identical), KRTAP9-1 (79% identical), KRTAP4-12 (50% identical), KRTAP4-6 (49% identical), KRTAP4-9 (47% identical), KRTAP4-11 (46% identical), KRTAP4-3 (43% identical), and 35 more.